BCL2 (BCL2 apoptosis regulator)
Diseases named in the same sentence as BCL2 in open-access papers (continued):
Sharing a sentence is not in itself a finding about the gene and the disease.
cancer (continued). "After 6 h, the total protein was extracted for phosphorylation protein microarray analysis, which found that AKT and GSK3β protein phosphorylation ratios in the sh-cancer-IgG group were reduced and that Bcl-2, BAD, caspase 3, caspase 9, and BAX apoptosis-related proteins increased." (PMID 34150640, 2021). "In LC, NLCs are often used to resolve p-glycoprotein (P-gp) efflux, and drug resistance which is generally associated with over-expression of MRP1 protein (responsible for cancer cell drug efflux) and BCL2 protein (responsible for anti-apoptotic cellular defense)." (PMID 34451824, 2021). "Moreover, depletion of TPT1 in HeLa cells or mice not only promoted apoptosis by BCL2 inhibition but enhanced the overall autophagy flux, two attractive strategies against cancer." (PMID 34589516, 2021). "Also, the key roles of the genes selected by the Laplacian score including IFN-γ, Foxp3, IL-4, BCL-2, Oct4 and survivin in the development of various cancers and their prognostic value have been clinically confirmed." (PMID 34181334, 2021). "there was no obvious difference between two groups in experiment A. However, in experiment B, similar to caspase-3, bax showed a higher expression in the treated group while bcl-2 showed a lower expression, indicating the enhanced immune system which promoted cancer cell apoptosis." (PMID 34993150, 2021). "Although the downstream targets of miR-519a-3p, such as STAT3/Bcl2, have been well-studied in cancer biology, its upstream regulators remain largely unknown." (PMID 34867700, 2021). "Ursolic acid also altered various apoptosis pathway components, such as the activation of caspase-3, -8, -9, and Bid along with the overexpression of Bax and reduction of Bcl-2 proteins, suggesting the promotion of intrinsic and extrinsic apoptosis in these cancer cells." (PMID 33916780, 2021). "The Bcl-2 gene is a kind of cancer gene, which can inhibit apoptosis." (PMID 33653412, 2021). "Moreover, the intracellular levels of Bax protein were considerably upregulated, while that of Bcl-2 protein was downregulated by miR-300 overexpression in both CaSki and HeLa cancer cell lines." (PMID 34950207, 2021). "However, TRAIL-induced apoptosis can bypass the intrinsic apoptosis pathway controlled by Bcl-2 in cancer." (PMID 33916015, 2021). "Inactivating mutations or deletions of pro-apoptotic Bax or Bak are rare, but many cancers, especially those being refractory to therapy, such as colon, gastric and leukemia, overexpress one or more pro-survival family members, including Bcl-2, Bcl-xL and Mcl-1." (PMID 34503172, 2021). "Bcl-2 protein inhibits apoptosis and is upregulated in many cancers." (PMID 33796026, 2021). "Bcl-2 mRNA was also targeted by MiRNA-34a as an important factor in cancer cells." (PMID 33906308, 2021). "It has been shown that Bcl-2 overexpression protects various cancer cells from apoptosis." (PMID 34360795, 2021). "In addition, overexpression of antiapoptotic protein BCL2 has been reported as a requirement for the genesis of cancer and resistance of cancer cells to apoptosis." (PMID 32183192, 2020). "Overexpression of Bcl-2 into cancer cells significantly decreased C5-induced apoptosis." (PMID 32075108, 2020). "In more recent studies, it has been reported that tumorigenesis could be abolished by inducing cell apoptosis via miRNA-mediated BCL2 downregulation in different cancer cells." (PMID 32366289, 2020). "Bcl-2 is a pro-survival molecule that is overexpressed in many cancers." (PMID 33348707, 2020). "IHT is an attractive candidate to develop as an anti-cancer drug due to its decrease in expression of Bcl-2, Mcl-1, XIAP, and Survivin in NCI-H460 tumorspheroids and its downregulation of Mcl-1 and Survivin in A549 with siNR4A1 to activate the intrinsic apoptosis pathway." (PMID 33172112, 2020).
cancer (continued). "In addition, our observed link between the integrin-dependent signaling and Akt or Bcl2-mediated cell survival pathway was consistent with prior studies on FAK in multiple cancer types, particularly those exhibiting frequent FAK amplification." (PMID 32793596, 2020). "Thus, the anti-apoptotic Bcl-2 proteins represent an interesting target for cancer therapy since its inhibition will unleash the pro-apoptotic function." (PMID 33396645, 2020). "The overexpression of Bcl2 in many cancer cells may inhibit the pro-apoptotic signals which allow cancer cells to survive under stress conditions." (PMID 33400732, 2020). "Thus, BDA-366 emerged as a promising anticancer tool for a variety of cancer types characterized by Bcl-2 overexpression." (PMID 32943617, 2020). "BH3-mimetics are a new class of anti-cancer drugs that inhibit anti-apoptotic Bcl-2 proteins." (PMID 32792521, 2020). "Therefore, the anti-apoptotic action of Bcl-2 contributes to the pathological phenotype of neoplastic cells, which allows cancer progression." (PMID 32365761, 2020). "Mcl-1 is one of the key targets in contemporary anti-cancer research along with Bcl-2 and Bcl-xL13." (PMID 33257694, 2020). "Fucoidan exhibits anticancer effect via increased Bax/Bcl-2 expression ratio in cancer cells." (PMID 32570707, 2020). "Although BCL-2 is overexpressed in a multitude of solid tumors and hematological malignancies, significant responses to venetoclax monotherapy are limited to only a handful of cancer types." (PMID 32131385, 2020). "Surprisingly, we found that upon vincristine treatment there were no significant changes in the anti-apoptotic proteins MCL-1, BCL-xL, or BCL-2 expression, indicating that cancer cells’ adaptation to this therapy relies on different mechanisms other than increased expression of these proteins." (PMID 32801295, 2020). "We showed a reduction in key cancer related proteins: BCL2, CDK6, p65 and JNK1 kinase, suggesting that reduction of the expression of these proteins might contribute to the effects of BORA depletion on cell survival." (PMID 32268485, 2020). "The Ki67, P21, Bcl-2, and Bax proteins also had cancer-related pathological characteristics." (PMID 32047812, 2020). "Bcl-2 enables cancer cells to evade apoptosis at two levels." (PMID 32943617, 2020). "In cancer, the acetylation state of histones and other proteins is altered, and BRDs promote the expression of many oncogenes, such as c-Myc and Bcl-2, and thus their inhibition provides a way to inhibit cancer cell growth (see also section Inhibitors of Transcription Factor Gene Expression)." (PMID 32373584, 2020). "Indeed, BCL-2 promotes mitochondrial respiration in cancer cells, resulting in a pro-oxidant state in basal conditions, while BCL-xL stabilizes the inner membrane potential and thus modulates mitochondrial energetics in neurons." (PMID 33080792, 2020). "We used Molt-4 and CEM cells as T-ALL model cancer cells and assessed the mechanism of cell death by evaluating mitochondrial (ratio Bax-Bcl-2, ROS and TMRE) and nuclear (γ-H2Ax, cell cycle, and DNA degradation) alterations and the role of ROS and caspases in cell death mechanism." (PMID 32587616, 2020). "Elevated expression of BCL-2 gene that encodes the anti-apoptotic BCL-2 protein greatly contributes to acquiring resistance for apoptosis in cancer cells, and its inhibition sensitizes cancer cells to apoptotic death." (PMID 32929356, 2020). "Quindoline, perylene and coronenen derivatives have been reported to downregulate Bcl-2 transcription and promoter activity and to induce apoptosis in cancer models but with a promiscuous mechanism of action affecting also other biological targets, such as telomeric and other oncogenic G4." (PMID 32455818, 2020). "In addition, betulinic acid, 23-hydroxybetulinic acid, betulin and lupeol have significant anti-cancer activities through activating mitochondrial apoptosis pathway, and regulate the levels of Bcl-2 and ROS." (PMID 33013373, 2020).
cancer (continued). "ELISA assay results largely mirrored the data obtained from Bcl-2 positive cancer cell lines." (PMID 33256166, 2020). "Other compounds identified in the Oenothera paradoxa extracts like quercetin or epigallocatechin-3-gallate inhibit cancer cell growth via the downregulation of anti-apoptotic factors (e.g., Bcl-2) and the induction of pro-apoptotic Bax, thus forcing cancer cells’ death." (PMID 33228230, 2020). "Moreover, BCL-2 acts as an apoptosis regulator and has been shown to play a critical role in the pathogenesis of various types of cancer." (PMID 32944040, 2020). "This may be explained by the influence of Bax in cancer development, and of Bcl-2 in its progression to stage IV." (PMID 32901694, 2020). "Although Bcl-2 is considered an anti-apoptotic gene and its overexpression is commonly associated with different types of human cancers, there is no solid evidence to show that Bcl-2 overexpression alone will induce carcinogenesis." (PMID 32859045, 2020). "The upregulation of Bcl-2 in cancer cells occurs via the inhibition of apoptosis." (PMID 32784981, 2020). "Indeed, the decrease in BCL-2 protein level induced by paclitaxel treatment is blocked by the integrin-mediated cell attachment of cancer cells to collagen I, fibronectin or laminin, although the induction of signals depends on the cell lines." (PMID 33080792, 2020). "Taken together, the results of this study showed that the reductions of anti-apoptotic proteins and alterations to MCL1 splicing is an important mechanism of CLK-induced cell death and the use of CLK inhibitors in combination with Bcl-xL/Bcl-2 inhibitors presents an option for cancer therapy." (PMID 33064779, 2020). "Thus, novel therapeutic strategies are urgently needed to target Mcl-1 and sensitize the anti-cancer activities of Bcl-2 inhibitors for effective treatment of NSCLC." (PMID 32587776, 2020). "Bcl-2 contributes to the survival of cancer cells by inhibiting pro-apoptotic protein activation." (PMID 32714093, 2020). "The proportion of Bax/Bcl-2 during the apoptotic process plays a key role in cancer progression." (PMID 32685496, 2020). "Similarly, following targeted drug regimen interfering with ER signaling in ER-positive cancers, cell survival and chemoresistance seem to be favored by mitochondrial increased activity of Bcl-2." (PMID 32517101, 2020). "Quercetin was reported to upregulate the expression of pro-apoptotic proteins (Bax and Bad) and downregulated the anti-apoptotic proteins, Bcl-2 and Bcl-xl, thereby suppressing cell proliferation and promoting the induction of apoptosis in various cancer cell lines." (PMID 32093300, 2020). "Besides, the overexpression of the PI3K/Akt signaling pathway facilitates the depolymerization of Bcl-xl and Bcl-2, resulting in the inactivation of Caspase-9 and Caspase-3, and finally leads to the growth and proliferation of cancer cells." (PMID 32495637, 2020). "In addition to serving as the promoter of metastasis and a regulator of cell invasion, Bcl-2 is known to be involved in the mediation of chemotherapy resistance in some types of cancers." (PMID 32922496, 2020). "JHU-012 and −019 cancer cells grown in co-culture were significantly less apoptotic (p < 0.001), expressed significantly higher levels of Bcl-2 (p < 0.04) with a concomitant significant decrease in bid expression (p < 0.001) compared to cancer cells grown alone." (PMID 32411595, 2020). "Mcl-1 overexpression confers acquired resistance to Bcl-2 inhibitors, and therefore we hypothesized that DYRK1A overexpression would also hinder the anti-cancer effects of Bcl-2 inhibitors." (PMID 32587776, 2020). "In addition, HMGB1/RAGE can regulate the expression of the BCL-2 gene (B-cell lymphoma/leukemia-2 gene), which is a cancer gene with the effect of inhibiting apoptosis." (PMID 33473353, 2020).
cancer (continued). "Local anaesthetics modify the protein levels of key members of the Bcl-2 family in a manner that presents an increase in the ratio of Bax/Bcl-2, which may contribute to the response of cancer cells to apoptosis." (PMID 32807213, 2020). "Thus, inhibiting the PPI between anti- and pro-apoptotic BCL-2 proteins, thereby directly induces apoptosis in cancer cells, is an attractive cancer therapeutic strategy." (PMID 34296214, 2020). "Moreover, anti-cancer effects should be studied correlating interactions with gene expressions, such as Bax and Bcl-2." (PMID 32385391, 2020). "Researchers in the past have identified Bcl-2 as a predictive marker of patient response to immunotherapy in clinical samples of metastatic renal cell carcinoma, raising the possibility of targeting Bcl-2 to enhance the vulnerability of cancer cells to immunotherapies." (PMID 35310881, 2020). "The upregulation of Bcl-2 is one of the predominant ways for cancer cells to evade apoptosis." (PMID 32872195, 2020). "However, what frequently occurs in cancer is the upregulation of the anti-apoptotic B-cell lymphoma 2 (Bcl-2) family of proteins, which consequently facilitates oncogenesis through cell death resistance." (PMID 32260280, 2020). "Collectively, our in vivo results corroborate the in vitro data on the bcl-2 ability to induce the recruitment of M2 macrophages and indicate the ability of cancer-specific bcl-2 to establish suppressive microenvironmental conditions that impair T cell responses." (PMID 32269145, 2020). "In the setting of solid tumours, it is therefore more challenging to determine which cancer type and which individual patients may best benefit from a given BCL-2 antagonist, highlighting the need for novel systems-based patient stratification tools." (PMID 33066609, 2020). "Importantly, it has been repeatedly demonstrated that cancer cells, whose anti-apoptotic BCL-2 proteins are occupied by BH3 domain-only activators are so-called “primed for death”." (PMID 32290241, 2020). "In conclusion, we believe that tetrahydro-4H-thiopyran-4-one-containing diarylpentanoids could be a new class of Bcl-2 inhibitor that deserves further investigation in the search for new anti-cancer agents." (PMID 32858795, 2020). "The discovery of cancer-promoting miRNAs has been accompanied also by the identification of many cancer-suppressing miRNAs, such as miR-15a and miR-16-1, which are able to inhibit tumorigenesis driven by the Bcl2 oncogene." (PMID 31949213, 2020). "This strategy resulted in proteins able to bind anti-apoptotic Bcl-2 proteins with increased affinity and specificity, and demonstrated that the designed inhibitors were able to induce apoptosis in cancer cells in vitro by engaging the BH3-binding grooves of specific pro-survival proteins." (PMID 32455818, 2020). "Thus, while BDA-366 and venetoclax inhibit Bcl-2 via distinct mechanisms, cancer cells that acquire resistance against venetoclax also seem to acquire resistance against BDA-366." (PMID 32708132, 2020). "Obatoclax antagonizes Bcl-2, Bcl-xL, Bcl-w and Mcl-1, thus leading to the activation of Bax/Bak, mitochondrial depolarization, cytochrome c release and subsequent activation of caspase-3, which consequently leads to apoptosis in cancer cells." (PMID 32367199, 2020). "Whether this approach may be useful has been argued to be dependent on several factor including the levels of Bcl-2 in different stages of cancer cells and their reliance on Bcl-2 for survival." (PMID 32344908, 2020). "BCL2 is believed to suppress apoptosis in a variety of tissues and cancers." (PMID 32973404, 2020).
cancer (continued). "Variations in priming are important for how both healthy and cancer cells respond to chemotherapeutic agents, but how it is dynamically coordinated by Bcl-2 proteins remains unclear." (PMID 33067418, 2020). "Only two of them (TM-(–)-18 and TM-(–)-4a) exerted anti-cancer activities with the loss of Mcl-1 and partly reduced Bcl-2, while the other analogues had no such effects." (PMID 32260280, 2020). "The ratio of BCL-2/bax determines the sensitivity of cancer cells to death signals." (PMID 32737339, 2020). "The imbalance of expression ratio of Bax/Bcl-2 reveals the growth status of cancer cells." (PMID 33094104, 2020). "Thus, there are a plenty of molecular studies and clinical trials in course to target BCL-2 proteins to cancer therapy." (PMID 32309275, 2020). "SiRNAs suppress cancer cell metastasis (MMP-9) andproliferation (Bcl-2)." (PMID 33095554, 2020). "Functional assays, such as through BH3 profiling, may facilitate prediction of treatment response, development of drug resistance and shed light on rational combinations of BCL-2 inhibitors with other branches of cancer therapy." (PMID 32131385, 2020). "In addition, each extract increased the level of the proapoptotic protein Bax and caspase-3 and decreased the level of the antiapoptotic protein Bcl-2 on HepG2 cancer cell line." (PMID 33294124, 2020). "However, also the targeting of Bcl-2’s BH4 domain recently emerged as a promising strategy to drive cancer cell death." (PMID 32943617, 2020). "Furthermore, the results of IHC showed the levels of Ki67 and Bcl-2 in xenografts derived from either cancer cells or PDX were also inhibited by GSK2879552." (PMID 32850370, 2020). "Indeed, in some cancer systems, early Cer accumulation occurs downstream of Bcl-2 action and mitochondrial pathway, whereas in others Cer production occurs upstream of these actions." (PMID 33048123, 2020). "For the apoptosis of cancer cells, the Bax/Bcl-2 ratio could provide the development on apoptosis and reflect the changes under different modulators." (PMID 33062725, 2020). "Studies have reported that Bcl2 is an anti‐apoptotic protein in cancers, whereas Bax has a pro‐apoptotic effect, and the radio of Bax to Bcl‐2 is used to determine whether the cells will commit to apoptosis." (PMID 31441181, 2020). "This hyperpolarization may be due to the increased intracellular Ca2+ levels and upregulation of anti-apoptotic Bcl-2 protein in the cancer cells." (PMID 32977472, 2020). "Higher expression of BCL2 has been reported in several cancers including leukemia and lymphoma." (PMID 32938954, 2020). "Anti-CXCR4 scFvs increased the Bax/Bcl-2 ratio in all three cancer cell lines." (PMID 33392074, 2020). "Furthermore, we observed the upregulation of cleaved caspase-3 and Bax with downregulation of anti-apoptotic Bcl-2, indicating the induction of cancer cell apoptosis." (PMID 32764438, 2020). "Accordingly, sclareol may have the potential to overcome cancer chemoresistance by inhibiting Bcl-2." (PMID 32922496, 2020). "Bcl-2 protein level is a most frequently used indicator for apoptosis resistance of cancer cells." (PMID 31901898, 2020). "The purpose of this review is to discuss the state-of-the-art in the development of drugs targeting Bcl-2 anti-apoptotic proteins and to highlight the potential of their application as single agents or in combination for improving anti-cancer therapy, focusing in particular on solid tumors." (PMID 32455818, 2020). "Moreover, Maritoclax was reported to sensitise a number of cancer cell lines to ABT-737 (first generation BH3 mimetic which inhibits BCL-2, BCL-XL and BCL-w) by down-regulating MCL-1." (PMID 33214852, 2020). "In relation to several cancers, it has been shown that Bcl-2 overexpression alone does not cause cancer, but simultaneous overexpression of an oncogene is required to induce carcinogenesis." (PMID 32859045, 2020).